FNBP1 (formin binding protein 1)
Diseases named in the same sentence as FNBP1 in open-access papers:
FNBP1 is named in the same sentence as 35 diseases in open-access papers, as found by Europe PMC text mining. Sharing a sentence is not in itself a finding about the gene and the disease. The quoted sentences say what the papers report.
breast carcinoma (10 papers, 2020 to 2024). "Remarkably, a pan-cancer analysis based on bioinformatics found that except the metastatic cancer, low expression of FNBP1 was associated with worse prognosis in breast cancer and lung adenocarcinoma, while high expression of FNBP1 was related to the poor prognosis in stomach adenocarcinoma." (PMID 37179366, 2023). "High expression of FNBP1 has a favorable prognosis for breast cancer and lung adenocarcinoma but an unfavorable prognosis for gastric adenocarcinoma." (PMID 38074028, 2023). "Only few studies have focused on migration and invasion, such as the three-dimensional movement of gastric cancer cells, suppression of FNBP1 affected the formation of filopodia in bladder cancer and breast cancer cells." (PMID 34998385, 2022). "For example, in the normal sample, FNBP1 was co-expressed with MGP, whose down-regulation is associated with better survival in breast cancer (scLink’s correlation = 0.77, adjusted P = 0)." (PMID 34252628, 2021). "Previously, FNBP1 was reported to indicate poor differentiation and invasiveness in breast cancer and bladder cancer." (PMID 34202606, 2021). "In order to correlate the expression of FBP17 in breast cancer tissues to the patient outcome, we have analyzed publicly available dataset, Tang_2018, Kaplan-Meier Plotter22 for FNBP1 (gene symbol for FBP17) and Q96RU3 (Uniprot ID for FBP17)." (PMID 32665637, 2020). "FNBP1 encodes the protein FBP17, and its upregulation is linked to good prognosis of breast cancer." (PMID 38398114, 2024). "Several researches showed that FNBP1 could affect tumor migration and invasion through affecting the formation of filopodia in bladder cancer and breast cancer cells." (PMID 37179366, 2023). "Taken together, expression of FNBP1 could be regarded as an effective prognostic indicator for breast cancers, lung adenocarcinomas and stomach adenocarcinoma depending on the clinical characteristics." (PMID 34998385, 2022).
bladder cancer (5 papers, 2020 to 2024). "FNBP1 upregulation appears to be associated with invasive tumours in breast, gastric, and bladder cancers." (PMID 38398114, 2024). "The high expression of FNBP1 is closely related to the formation of invadopodia in breast, gastric, and bladder cancer, which supports the highly invasive characteristics of tumor cells." (PMID 34998385, 2022). "Although the studies on FNBP1 in cancer cells are marginal, FNBP1 has been reported to have a role in invadopodia formation in breast and bladder cancer." (PMID 34202606, 2021). "However, a study analysing tumours without specified invasiveness observed that FNBP1 was upregulated in favourable prognosis of cancers including breast, lung, cervical and bladder cancer." (PMID 38398114, 2024).
bladder tumor (5 papers, 2015 to 2022). "Formation of invadopodia and invasive phenotype of bladder tumor cells involve Formin Binding Protein 17 (FBP17) belonging to the family of formin-binding proteins which regulate the formin-dependent actin assembly." (PMID 34294140, 2021). "FNBP1 promoted invadopodia formation and invasive capacity in bladder tumor cells." (PMID 35201476, 2021). "The expression levels of a portion of feature genes, such as ANGPTL2, CAV1, FNBP1, FXD6, MAP1A, and ZCCHC24 were significantly decreased in bladder tumor cell lines." (PMID 35719407, 2022).
stomach adenocarcinoma (4 papers, 2021 to 2023). "Besides, FNBP1 had a correlation with various immune infiltrating cells and diverse immune gene markers in breast invasive carcinoma (BRCA), lung adenocarcinoma (LUAD), and stomach adenocarcinoma (STAD)." (PMID 34998385, 2022).
ductal carcinomas (3 papers, 2020 to 2025). "Previous studies found that FNBP1 was overexpressed in invasive breast cancer cells and ductal carcinomas, regulating the cytoskeleton and metastasis." (PMID 35201476, 2021).
gastric cancer (3 papers, 2021 to 2023). A primary or metastatic malignant neoplasm involving the stomach. "The expression level of FNBP1 is positively associated with infiltrating immune cells in breast, ovarian, lung and gastric cancers." (PMID 34998385, 2022). "In addition, a recent study found the loss of FNBP1 could result in the loss of invasive ability in gastric cancer." (PMID 37179366, 2023). "In an effort to identify the critical factors contributing to the aggressive behavior of gastric cancer, we found that FNBP1 expression is correlated with the worst prognosis." (PMID 34202606, 2021).
lung adenocarcinoma (3 papers, 2022 to 2023). A carcinoma that arises from the lung and is characterized by the presence of malignant glandular epithelial cells. "In addition, elevated FNBP1 expression was correlated with better OS or DFS in KIRC (kidney renal clear cell carcinoma), LUAD (lung adenocarcinoma) and THYM (thymoma)." (PMID 34998385, 2022).
osteosarcoma (3 papers, 2021 to 2024). A usually aggressive malignant bone-forming mesenchymal neoplasm, predominantly affecting adolescents and young adults. "For example, LINC00987 binds to miR-376a-5p by competing with FNBP1 to promote osteosarcoma cell development." (PMID 38910243, 2024). "Silencing LINC00987 inhibits proliferation, migration, and invasion of osteosarcoma cells by sponging miR-376a-5p to regulate FNBP1 expression." (PMID 35201476, 2021). "The results revealed an abundance of LINC00987 through sponging miR-376a-5p and positive regulation of FNBP1 protein level, consequently contributing to the proliferation, migration, and invasion of osteosarcoma cells." (PMID 35201476, 2021). "In conclusions, this study suggests LINC00987 silencing inhibits osteosarcoma cell proliferation, migration, and invasion by sponging miR-376a-5p to regulate FNBP1 expression." (PMID 35201476, 2021). "FNBP1 expression was increased in osteosarcoma cells; however, it was inhibited by silencing LINC00987 and enhanced by silencing miR-376a-5p." (PMID 35201476, 2021). "FNBP1 protein levels were significantly increased in osteosarcoma cells, particularly in 143B and U2OS cells, compared to those in hFOB1.19 cells, which was similar with the expression trends of LINC00987." (PMID 35201476, 2021). "Additionally, silencing of LINC00987 inhibited FNBP1 levels, whereas silencing miR-376a-5p promoted FNBP1 levels, through posttranscriptional regulation in osteosarcoma." (PMID 35201476, 2021). "Similarly, in this study, we found that FNBP1 is overexpressed in osteosarcoma." (PMID 35201476, 2021).
glioma (2 papers, 2017 to 2022). A benign or malignant brain and spinal cord tumor that arises from glial cells (astrocytes, oligodendrocytes, ependymal cells). "However, among the other common tumors, high FNBP1 expression was correlated with a worse ending than low FNBP1 expression in glioma and colorectal cancer." (PMID 34998385, 2022).
aneurysm (1 paper, 2021). Bulging or ballooning in an area of an artery secondary to arterial wall weakening. "Upon studying these genes for a possible role in MFS, four genes (FNBP1, EHBP1, SDK1, and PTPRN2) were found to be involved in cytoskeletal actin dynamics, which regulates cell-adhesion and cellular uptake or secretion, which is altered in MFS cells, and thought to play a role in aneurysm formation." (PMID 34895303, 2021).
asthma (1 paper, 2024). "By using the LASSO algorithm, we identified five shared eosinophil‐associated hub genes (PPP1R14A, FNBP1, DRAM1, FSCN1, and MMP12) in asthma and CC." (PMID 39659035, 2024).
cervical cancer (1 paper, 2023). A primary or metastatic malignant neoplasm involving the cervix. "The chemosensitization of cervical cancers using traditional drugs in combination with the silencing of FNBP1 were assessed, the outcomes of which guaranteed FNBP1 a promising target for cervical cancers in combination therapy." (PMID 37566043, 2023). "Here, FNBP1 was confirmed to play a crucial role in maintaining constitutive FAK/PI3K/AKT/mTOR survival signaling in cervical cancer cells." (PMID 37566043, 2023). "The same results were experimentally acquired, which indicated that FNBP1 played a ubiquitous role in cervical cancer cell survival by FAK/PI3K/AKT signaling." (PMID 37566043, 2023). "Promisingly, FNBP1 would be among these important target genes in cervical cancer treatments." (PMID 37566043, 2023). "Here, FNBP1 was also demonstrated to play a crucial role in cervical cancer cell survival, and the knockdown of which could result in the attenuation of FAK/PI3K/AKT signaling followed by significant apoptotic accumulation and proliferative inhibition." (PMID 37566043, 2023). "Promisingly, FNBP1 might be a potential target against cervical cancer in combination therapy." (PMID 37566043, 2023).
co-infection (1 paper, 2016). "Microarray analysis revealed that upregulation of FNBP-1 gene expression at baseline appears as a marker of a clinical state characterized by increased vulnerability for subsequent NI in association with HIV/HCV co-infection and to lesser degree to HCV mono-infection." (PMID 28255515, 2016).
medulloblastoma (1 paper, 2021). A malignant, invasive embryonal neoplasm arising from the cerebellum. "FNBP1 expression was increased in pediatric medulloblastoma, which may act as prognostic markers and therapeutic targets." (PMID 35201476, 2021).
metastatic tumors (1 paper, 2022). "Analyses of prognostic values show that in BRCA and LUAD, besides the metastatic tumors, low levels of FNBP1 are associated with a worse prognosis." (PMID 34998385, 2022). "Overall, high FNBP1 expression indicates favorable prognosis in the most of cancers beside for some metastatic tumors." (PMID 34998385, 2022).
neuroblastoma (1 paper, 2024). Neuroblastoma (NB) is the most common solid, extracranial childhood tumor. "Therefore, FNBP1 could be analysed on different neuroblastoma stages." (PMID 38398114, 2024).
testicular cancer (1 paper, 2022). A primary or metastatic malignant neoplasm that affects the testis. "In addition, Kaplan–Meier plotter analysis indicated decreased FNBP1 expression was related to short survival in breast, lung, cervical, esophageal, head-neck, kidney renal clear carcinoma, bladder, and testicular cancer patients." (PMID 34998385, 2022).
cancer (12 papers, 2011 to 2024). A tumor composed of atypical neoplastic, often pleomorphic cells that invade other tissues. "We purposed to explore the correlations of FNBP1 expression, prognosis and immune infiltration levels in various cancers." (PMID 34998385, 2022). "The expression level of FNBP1 is closely positively correlated with the expression level of multiple immune checkpoints in the three cancers." (PMID 34998385, 2022). "The results showed that, in these three cancers, after tumor purity correction, FNBP1 was positively correlated in varying degrees with most immune markers." (PMID 34998385, 2022). "Our findings reveal FNBP1 can serve as a significant biomarker to influence the prognosis and the immune infiltrating levels in different cancers." (PMID 34998385, 2022). "FNBP1 expression patterns rest with the type of tumor, suggesting that FNBP1 expression can be considered as a predictive and potential marker in cancer." (PMID 34998385, 2022). "Analyzing FNBP1 mRNA levels in various tumors and normal samples with the Oncomine database, among various cancer types, FNBP1 is significantly under-expressed in most cancer sample data sets." (PMID 34998385, 2022). "We analyzed the mRNA expression levels of FNBP1 and the prognostic phenotype in various cancers comprehensively." (PMID 34998385, 2022). "We comprehensively analyzed the expression of FNBP1 and its correlation with the prognostic value of pan-cancer through different databases, including Oncomine, TIMER (tumor immunity estimation resource), GEPIA, PrognoScan, and Kaplan–Meier plotter." (PMID 34998385, 2022). "Another project we are focusing on is to explore the mechanism of FNBP1 in tumorigenesis of various cancers and its relationship with immune infiltration in animal experiments in vitro and in vivo." (PMID 34998385, 2022). "This seems to be inconsistent with the results of our data analysis, but the cancer progression associated with high FNBP1 is mostly manifested in invasive tumor cells, such as SKCM/SKCM-metastasis group in TIMER-Pan-cancer analysis." (PMID 34998385, 2022). "FNBP1 drives cell motility, which is essential for the invasive or metastatic characteristics of the cancer." (PMID 34202606, 2021). "Unlike other organs which show relatively uniform up-regulation of FNBP1 across the cell lines, stomach and large intestine cancer cell lines revealed a wide range of FNBP1 expression levels, indicating its potential to be the subtype-specific marker." (PMID 34202606, 2021). "Since GC cell lines have a wide range of FNBP1 expression across the cell lines compared to other cancer cell lines from different organs, it is important to find the transcription driver." (PMID 34202606, 2021). "To elucidate the significance of PC4 with respect to SMYD3 transactivation, we next investigated PC4 localization at the FNBP1 and MFGE8 genes by ChIP assays employing cross-linked chromatin isolated from control and SMYD3-depeleted cancer cells." (PMID 26350217, 2015). "FNBP1 has significant and complex effects on the prognosis of kinds of cancers." (PMID 34998385, 2022). "Thus, the correlation between FNBP1 and tumor-infiltrating immune cells was assessed in different cancers with TIMER." (PMID 34998385, 2022). "Therefore, further research is needed to verify the role of FNBP1 in interested cancers using these models." (PMID 34998385, 2022). "Seven out of twelve cancers presented a potential correlation between FNBP1 and prognosis." (PMID 34998385, 2022). "We have observed that FNBP1 is widely expressed in various cancers, and may affect survival time by interacting with infiltrating immune cells." (PMID 34998385, 2022). "Consequently, we performed FNBP1 expression in multiple human cancers microarray RNA-seq data from The Cancer Genome Atlas (TCGA)." (PMID 34998385, 2022).
cancer (continued). "Mutations in the mismatch repair gene PMS1 and the actin cytoskeleton remodelling gene FNBP1 were subclonally fixed in hEMT cancers, potentially suggesting that acquiring such alterations later during tumour evolution may benefit the establishment of a hybrid phenotype." (PMID 36774358, 2023). "However, FNBP1 expression shows a better prognosis in most cancers." (PMID 34998385, 2022). "FNBP1, FRMD3, IGSF10, IL11RA, and TOX2 have known roles in cancer." (PMID 38398114, 2024). "In the process of cancer, the correlation between FNBP1 and immune markers changes from negative to positive." (PMID 34998385, 2022). "Since there is a wide range of differences in FNBP1 expression level in GC cell lines, unlike most other cancer cell lines of different organs, the FNBP1 promoter region is re-visited to identify its transcription driver." (PMID 34202606, 2021). "In this study, we introduce FNBP1 as a distinguisher not between normal tissues and carcinoma, but between EMT and non-EMT type cancer cells in GC, supported by transcriptomic analysis of GC patients and in vitro experiments." (PMID 34202606, 2021). "Even though four (PIK3C2A, JUN, FNBP1, ITPR1) of our peripheral biomarkers have been implicated in cancer pathophysiology, none of the PBMC biomarkers were differentially expressed between tumor types (among all subjects, or within cases or controls alone)." (PMID 21884629, 2011).
tumor (10 papers, 2011 to 2024). "Compared with normal tissues, FNBP1 is significantly differentially expressed in a variety of tumor tissues." (PMID 34998385, 2022). "The high correlation between FNBP1 and many immune checkpoints reminds us: Abnormal membrane actin skeleton assembly ability is a necessary condition for tumor cell metastasis." (PMID 34998385, 2022). "At present, the research on the mechanism of FNBP1 supporting tumor cell invasion and migration is very limited." (PMID 34998385, 2022). "Interestingly, when PDE9A, CADM3, and FNBP1 were used as co-predictors, they all showed low expression in tumor tissue, suggesting their potential use as biomarkers for predicting CRC." (PMID 37446311, 2023). "Thus, in the next task, more numerous samples are required to provide more clear evidence to confirm the effect of FNBP1 on tumor immune infiltration." (PMID 34998385, 2022). "FNBP1 expression in 28 types of tumors was evidently correlated with tumor purity." (PMID 34998385, 2022). "FNBP1 was also positively correlated with the adjustment of CD8+ cells, T cells, M2 macrophage, neutrophils, monocyte, Th1 cells, T regulatory cells (Treg) and Tumor-associated macrophages (TAMs)." (PMID 34998385, 2022). "Members of CIP4 family particularly Transducer of cdc-42 dependent actin assembly protein 1 (TOCA-1), Cdc-42 interacting protein 4 (CIP4), Formin Binding protein 17 (FBP17) have been studied previously and were found to contribute in promoting invadopodia formation and tumor metastasis." (PMID 32665637, 2020). "Therefore, the high expression of FNBP1 not only provides the motivation for tumor cell metastasis but also has a strong relationship with the potential association of immune checkpoints that prevent tumors from surveillance attacks by the immune system during metastasis." (PMID 34998385, 2022). "However, in tumor research, independent research on FNBP1 is extraordinarily limited." (PMID 34998385, 2022). "Formin-binding protein 1/17 (FNBP1/FBP17), as a membrane-bound protein, is wildly expressed in eukaryotic cells and performs a critical role in tumor tumorigenesis and progression." (PMID 34998385, 2022). "Therefore, this study offers new visions into the immunoregulatory function of FNBP1 in BRCA, LUAD, and STAD and its application as a tumor biomarker." (PMID 34998385, 2022).
psychiatric disorder (1 paper, 2016). A disorder characterized by behavioral and/or psychological abnormalities, often accompanied by physical symptoms. "Additionally, CME represents the primer mechanism of vesicle retrieval in hippocampal synapses, which indicates a further pathway of how FNBP-1 might be implicated in the regulation of CNS functions potentially relevant for the pathogenesis of psychiatric disorders." (PMID 28255515, 2016).
FNBP1 also shares sentences with these, for which no sentence is quoted: invasive breast carcinoma (3 papers); leukemia (2); acute myeloid leukemia (1); adrenocortical carcinoma (1); astrocytoma (1); autoimmune disease (1); breast tumors (1); colorectal cancer (1); infection (1); invasive ductal carcinomas (1); lung squamous cell carcinoma (1); metastatic cancer (1); rheumatoid arthritis (1); thymoma (1); uveal melanoma (1).